TAS2R19 (taste 2 receptor member 19)
Description:
Receptor that may play a role in the perception of bitterness and is gustducin-linked. May play a role in sensing the chemical composition of the gastrointestinal content. The activity of this receptor may stimulate alpha gustducin, mediate PLC-beta-2 activation and lead to the gating of TRPM5 (By similarity).
Synonyms: T2R48; TAS2R23; TAS2R48; T2R19; T2R23; MSTP058
Tractability: Antibody: its Gene Ontology location is reachable by antibodies, with high confidence; UniProt predicts a signal peptide or a membrane-spanning region. PROTAC: a small molecule that binds it is known.
Target class: Membrane receptor; Taste receptor (taste family GPCR); Taste family G protein-coupled receptor
Gene: Protein-coding gene on chromosome 12 (11,021,619 to 11,022,620, reverse strand). Ensembl gene ENSG00000212124.
Subcellular location: Membrane
Pathways (Reactome):
Signal Transduction: Class C/3 (Metabotropic glutamate/pheromone receptors); G alpha (i) signalling events
Gene Ontology:
Molecular function: bitter taste receptor activity; protein binding; G protein-coupled receptor activity
Biological process: detection of chemical stimulus involved in sensory perception of bitter taste; G protein-coupled receptor signaling pathway; sensory perception of taste
Cellular component: membrane; plasma membrane
Genetic constraint (gnomAD): Missense variants: 336 observed, 333.68 expected, observed/expected ratio (o/e) 1.01, 90% interval 0.92 to 1.1. Synonymous variants: 108 observed, 121.46 expected, observed/expected ratio (o/e) 0.89, 90% interval 0.76 to 1.04.
Homologues: Orthologues: chimpanzee TAS2R19 (96% identical), dog CAFA-T2R43 (60% identical), mouse Tas2r120 (48% identical), rat Tas2r136 (47% identical), rat Tas2r120 (47% identical), mouse Tas2r136 (45% identical). Paralogues in human: TAS2R20 (70% identical), TAS2R46 (69% identical), TAS2R30 (68% identical), TAS2R31 (68% identical), TAS2R43 (66% identical), TAS2R50 (65% identical), TAS2R14 (44% identical), TAS2R13 (43% identical), TAS2R9 (37% identical), TAS2R7 (36% identical), TAS2R8 (36% identical), TAS2R10 (35% identical), and 11 more.
Diseases named in the same sentence as TAS2R19 in open-access papers:
TAS2R19 is named in the same sentence as 9 diseases in open-access papers, as found by Europe PMC text mining. Sharing a sentence is not in itself a finding about the gene and the disease. The quoted sentences say what the papers report.
breast carcinoma (1 paper, 2022). "The TAS2Rs with highest expression in HNSCC (TAS2R4, TAS2R14, TAS2R19, TAS2R20, TAS2R30, TAS2R43, and TAS2R45) overlap with TAS2Rs expressed at increased levels in breast cancer." (PMID 34717036, 2022).
colon cancer (1 paper, 2024). "Utilizing univariate Cox regression analysis, we identified seven TAS2Rs genes associated with prognosis in colon cancer patients, including TAS2R4, TAS2R5, TAS2R14, TAS2R19, TAS2R20, TAS2R31, and TAS2R38." (PMID 38999959, 2024). "Our results show that compared to normal colon tissue, the expression levels of multiple bitter taste receptor genes are elevated in colon cancer tissue, including TAS2R4, TAS2R5, TAS2R14, TAS2R19, TAS2R20, TAS2R31, and TAS2R38." (PMID 38999959, 2024). "Differential expression analysis results revealed that compared to normal colon tissue, colon cancer samples exhibited elevated expression levels of TAS2R1, TAS2R4, TAS2R5, TAS2R14, TAS2R19, TAS2R20, and TAS2R38 (p < 0.05), with the exception of TAS2R60, which was downregulated." (PMID 38999959, 2024).
diabetes (1 paper, 2025). "Additionally, rs77837442 in TAS2R19 was associated with reduced anti-nucleocapsid antibody levels in individuals without diabetes (OR: 0.23; CI: 0.04, 0.71; p = 0.036)." (PMID 41153757, 2025).
tumor (1 paper, 2022). "Changes in expression for TAS1R1, TAS1R3, TAS2R4, TAS2R5, TAS2R14, TAS2R19, and TAS2R20 had survival associations in at least one tumor histology." (PMID 35624283, 2022).
TAS2R19 also shares sentences with these, for which no sentence is quoted: Alcohol Use Disorders (1 paper); cancer (1); leukemia (1); melanoma (1); neuroblastoma (1).